RNU6-130P (RNA, U6 small nuclear 130, pseudogene)
Gene: Small nuclear RNA gene on chromosome 6 (82,210,338 to 82,210,440, reverse strand). Ensembl gene ENSG00000223044.
Homologues: Orthologues: chimpanzee U6 (98% identical), macaque U6 (96% identical), rabbit U6 (84% identical). Paralogues in human: RNU6-1094P (89% identical), RNU6-454P (88% identical), RNU6-1209P (87% identical), RNU6-1310P (87% identical), RNU6-797P (87% identical), RNU6-1083P (86% identical), RNU6-1123P (86% identical), RNU6-11P (86% identical), RNU6-1243P (86% identical), RNU6-183P (86% identical), RNU6-204P (86% identical), RNU6-255P (86% identical), and 1289 more.